SMARCAL1 (SNF2 related chromatin remodeling annealing helicase 1)
Diseases named in the same sentence as SMARCAL1 in open-access papers (continued):
Sharing a sentence is not in itself a finding about the gene and the disease.
tumor (10 papers, 2018 to 2025). "In summary, SMARCAL1 expression exhibited close associations with genes involved in tumor immune modulation." (PMID 39994264, 2025). "In mouse models, SMARCAL1 deficiency significantly inhibited tumor growth and increased animal survival." (PMID 39247620, 2024). "SMARCAL1‐deficient tumor cells show higher levels of IRF3 phosphorylation and reduced levels of PD‐L1." (PMID 39247620, 2024). "unveiled a novel player in the intricate game of tumor immune evasion: SMARCAL1, linked to DNA repair, emerges as a dual regulator with a surprising ability to modulate both innate immune signaling and PD‐L1 expression." (PMID 39247620, 2024). "D06MG is a primary GBM cell line harboring a nonsense, homozygous SMARCAL1 mutation (W479X), derived from the tumor of patient DUMC-06." (PMID 29802247, 2018). "Moreover, treatment of SMARCAL1‐deficient B16/F10 tumors with anti‐PD‐L1 antibody or anti‐CTLA‐4 antibody significantly reduced tumor growth and improved animal survival." (PMID 39247620, 2024). "Recent targeted screening efforts have identified the DNA translocase SMARCAL1 as a factor inhibiting the immune response of tumor cells due to its dual role in restricting innate immune signaling and upregulating PD-L1 levels." (PMID 39994264, 2025). "Our study aimed to investigate the connection between the tumor immune microenvironment or immune cells that infiltrate tumors and SMARCAL1 expression." (PMID 39994264, 2025). "In particular, effectively using the immune system to combat tumors remains a substantial challenge due to tumor immunosuppressive factors such as SMARCAL1." (PMID 40650655, 2025). "Targeting SMARCAL1 can synergize with ICIs to treat tumors, providing a novel and effective approach to tumor immunotherapy." (PMID 39247620, 2024). "Among the 23 ALT-positive cases with exome sequencing data in paired tumor/normal samples, ATRX mutations were found in six samples, and a SMARCAL1 mutation was identified in one case." (PMID 32984050, 2020). "Restoration of SMARCAL1 expression in these cell lines significantly reduced colony forming ability, supporting the role of SMARCAL1 as a tumor suppressor." (PMID 29802247, 2018). "Initially, for a comprehensive demonstration of SMARCAL1 expression profiles in tumor and adjacent tissues, we observed elevated levels of SMARCAL1 expression across multiple tumor cell lines, notably in the bowel, uterus, lymphoid, lung, liver, and brain as documented in the CCLE dataset." (PMID 39994264, 2025). "Interestingly, in KIRC tumor tissues, SMARCAL1 mRNA expression levels were higher than in normal tissues, yet significantly correlated with favorable prognosis." (PMID 39994264, 2025). "However, we observed a notable increase in promoter methylation levels in KIRC, consistent with prior reports of elevated SMARCAL1 expression but favorable prognosis in KIRC tumor tissues." (PMID 39994264, 2025). "Moreover, blocking SMARCAL1 inhibits PD‐L1 expression and enhances the recognition and destruction of tumors by tumor‐specific T cells." (PMID 40650655, 2025). "sheds light on a previously unknown mechanism of tumor immune evasion and highlights the potential of targeting SMARCAL1 as a novel therapeutic strategy." (PMID 39247620, 2024). "Further evaluation of SMARCAL1‐mediated antitumor effects in mouse tumor models is needed." (PMID 39247620, 2024). "Literature regarding the relationship between SMARCAL1 and neoplasia is poor." (PMID 33203071, 2020). "Consistent with the analysis in our tumor samples, SLX4IP deficiencies in our cell lines are mutually exclusive with ATRX, DAXX, SMARCAL1, and H3.3, raising the possibility that SLX4IP may represent another gene deficiency associated with ALT activity." (PMID 31447390, 2019). "We described a glucose‐responsive CRISPR‐based nanovaccination with SMARCAL1 blockade to enhance STING signaling and inhibit the opposing functions of interferons, thereby suppressing tumor growth." (PMID 40650655, 2025).
tumor (continued). "Our results show that UCEC’s low-SMARCAL1 group has larger amounts of CD8 T cells, while other tumor types often have lower levels of CD8 and CD4 T cells." (PMID 39994264, 2025). "More research is needed to fully understand the impact of systemic therapeutic SMARCAL1 suppression on host immune cells, especially in light of possible negative feedback against anti-tumor immunity." (PMID 39994264, 2025).
renal disease (4 papers, 2016 to 2022). "Based on these findings, we hypothesized that SMARCAL1 deficiency causes the renal disease of SIOD by altering gene expression." (PMID 27816064, 2016). "We hypothesized that SMARCAL1 deficiency leads to gene expression changes that contribute to the pathogenesis of the renal disease in SIOD." (PMID 27816064, 2016). "We conclude that increased Wnt and Notch activity result from SMARCAL1 deficiency and, as established causes of FSGS, contribute to the renal disease of most SIOD patients." (PMID 27816064, 2016).
metabolic disorders (1 paper, 2023). "In addition to these genes, variants were found in seven genes (ALDOB, MASP1, KIAA1109, TRAPPC4, SMARCAL1, HERC1, RRAS2) that were previously not reported in MPS but associated with other metabolic disorders." (PMID 37091798, 2023).
SMARCAL1 also shares sentences with these, for which no sentence is quoted: skeletal dysplasia (3 papers); T cell deficiency (3); arteriosclerosis (2); autoimmune disease (2); autosomal recessive disease (2); genetic disease (2); spondyloepiphyseal dysplasia (2); T-cell immunodeficiency (2); Alpha-thalassemia (1); arterial disease (1); ataxia telangiectasia (1); atypical hemolytic-uremic syndrome (1); cervical cancer (1); developmental delay (1); dwarfism (1); dysplasia (1); emphysema (1); endometrial cancer (1); endometriosis (1); Ewing sarcoma (1); FILS syndrome (1); Hypertension (1); Hypoalbuminemia (1); kidney (1); liver cancer (1); meningioma (1); mental retardation (1); mesoblastic nephroma (1); moyamoya angiopathy (1); nephrotic syndrome (1).
A further 7 diseases each share a sentence with SMARCAL1 in 1 paper.